HIF1A (hypoxia inducible factor 1 subunit alpha)
Diseases named in the same sentence as HIF1A in open-access papers (continued):
Sharing a sentence is not in itself a finding about the gene and the disease.
tumor (continued). "Topotecan chemotherapy is used in the clinic to treat small cell lung cancer and overian cancer, and therefore can be a good candidate to study future HIF-1α inhibition studies in modulating tumor metabolism." (PMID 26962408, 2016). "It has been well known that hypoxia-induced HIF-1α mediates the down-stream signaling pathways for various forms of genes for response to tumor progression and invasion." (PMID 26822586, 2016). "Vascular endothelial growth factor (VEGF), a major paracrine mediator in the pathogenesis of glioblastomas and tumor angiogenesis, is also induced by HIF-1α." (PMID 27285755, 2016). "In the tumor mass, tumor and stromal cells produce substantial amounts of ROS and the endogenous ROS production by the tumor cells regulates angiogenesis and tumor development through HIF-1α and VEGF." (PMID 27286448, 2016). "We found that the growth of the tumor xenografts was significantly inhibited by wortmannin, while immunohistochemical staining showed HIF-1a and CD34 expression was significantly decreased." (PMID 27456341, 2016). "SEPT9 can be localized to nucleus, where it stabilizes HIF1-α and c-Jun and promotes tumor angiogenesis and cell proliferation." (PMID 27708241, 2016). "Certain factors, including HIF-1α, improve tumor adaptation to hypoxia and are involved in radioresistance." (PMID 27226982, 2016). "Collectively, the loss of Hif-1α in myeloid cells attenuated CYP-mediated metabolic activation of PAHs, subsequent in vivo and ex vivo DNA damage, and reduced tumor development." (PMID 27015123, 2016). "A considerable amount of evidence shows that HIF1α plays a tumor-suppressive role in VHL-defective renal carcinogenesis." (PMID 26743088, 2016). "Whereas, under hypoxic conditions, HIF-1α remains unhydroxylated and facilitates several factors, such as angiogenesis, tumour proliferation, tumour survival, and glycolysis." (PMID 27581969, 2016). "A hypoxic environment is a stimulus factor for tumor angiogenesis, and hypoxia inducing factor-1α (HIF-1α) is a key hypoxic response regulator that promotes the expression of VEGF-A, which is also a downstream component of the PI3K/Akt/mTOR signaling pathway." (PMID 26894862, 2016). "HIF-1α is situated at the convergence of multiple oncogenic and tumor suppressor pathways, including the PI3K/AKT and MAPK/ERK pathways." (PMID 27456341, 2016). "CCL2 regulates the infiltration of monocytes/macrophages and is reflected in tumor sites; in addition, HIF-1α is a critical transcriptional factor." (PMID 27271610, 2016). "We found that although metastasis tumor cell lines equally expressed HER2 compared to the mammary and DTC tumor cell lines, they showed higher HIF-1α levels compared to DTC tumor cell line." (PMID 27105499, 2016). "HIF1α is upregulated in areas of tumor hypoxia, and if translocated into the nucleus and bind to HIF1β can induce transcription of VEGF, thus increasing the formation of more blood vessels." (PMID 27018053, 2016). "Hypoxia and increased HIF-1α activity in tumor tissues in general correlate with poor prognosis of cancer patients." (PMID 26904023, 2016). "Macrophages play a crucial role in this setting as they can inhibit T cell-mediated tumor cell killing in a hypoxia/HIF-1α-dependent manner." (PMID 27034586, 2016). "Both hypoxia and HIF-1α activation in tumor angiogenesis are illuminated, but their roles in regulating VM are still puzzling." (PMID 27806701, 2016). "It has been shown that TPT reduces HIF-1α expression leading to decreased VEGF also in NB and is associated with tumor shrinkage." (PMID 26657295, 2016). "Studies have shown that the up-regulation of HIF-1α expression is one of the predictive factors for a poor prognosis in many tumor patients." (PMID 26985249, 2016). "Hypoxia-inducible factor-1α (HIF-1α) facilitates the biological response to hypoxia, advancing angiogenesis and metastatic potential of the tumor." (PMID 27780920, 2016).
tumor (continued). "In contrast, tumor frequency in Hif-1αLysM−/− as well as in Hif-1α/2αLysM−/− mice was significantly diminished, basically being absent." (PMID 27015123, 2016). "Results showed that the epithelial island regressed after TPF chemotherapy, but the expression levels of TFE3 and HIF-1α evidently increased in the residual tumor island when compared with paired biopsy (P < 0.01)." (PMID 26872381, 2016). "Compared to strong expression of both proteins in tumor tissues, ulcerous tissues demonstrated only marginal expression of both HIF1α and OATP1B3." (PMID 27329598, 2016). "Next, to determine the contribution of HIF-1α in DKG-mediated tumor propagation, MDA-MB-231/shCON or/shHIF-1α cells were pre-treated with DKG, and then injected into the flanks of NSG mice." (PMID 27058900, 2016). "The DKG-treated tumor cells were relatively resistant to IR, and this phenomenon was reversed in the HIF-1α knockdown tumor cells." (PMID 27058900, 2016). "By utilizing a bioluminescence imaging technique, we were able to demonstrate that PIN1 inhibition dramatically reduced the tumor volume in a subcutaneous mouse xenograft model and angiogenesis as well as hypoxia-induced transcriptional activity of HIF-1α." (PMID 26784107, 2016). "The fact that hypoxia-mediated effects persist even upon the inhibition of adipocyte-driven lipolysis speaks to the importance of HIF-1α signaling in driving the Warburg phenotype in tumor cells." (PMID 27588494, 2016). "Hypoxia-inducible factor-1α (HIF-1α), a regulatory transcription factor, plays a crucial role for tumor cells in responding to lower oxygen in their resident microenvironment." (PMID 26822586, 2016). "The expression of HIF-1α was predominantly detected in the nuclei of tumor cells around necrosis and was also found in the tumor cells not directly adjacent to necrotic area." (PMID 27244880, 2016). "HIF-1α and Ki-67 (a marker for cell proliferation) were less expressed, and vessels were poorly developed in tumor specimens from diacetoxyscirpenol-treated mice." (PMID 27613833, 2016). "The anthracycline increased HIF-1α amount and nuclear translocation, and Pgp levels in tumor extracts: these effects were fully prevented by NZ, which decreased HIF-1α and Pgp amount below the control." (PMID 26980746, 2016). "As a subunit of HIFs regulated by oxygen levels, HIF-1α can trigger a set of adaptive transcriptional responses to regulate tumor stem cell differentiation and self-renewal." (PMID 26831659, 2016). "Since HIF-1α was more stable with longer half-life in activity under hypoxia, leading to promote tumor angiogenesis, we further measured the expressions of HO-1 and VEGF in HCT-15 cells culturing in hypoxic condition." (PMID 26822586, 2016). "Hypoxia, a central feature of the tumor microenvironment, drives the expression of hypoxia-inducible factors on tumor cells including HIF1α, which regulates expression of genes involved in metabolism, angiogenesis, cell survival, and inflammation." (PMID 27437104, 2016). "HILPDA is a direct target of HIF-1α and PPARα, and elevated expression in hypoxia increases the number of lipid droplets in tumor cells." (PMID 27765905, 2016). "If this is true, PD1 inhibition will restore hypoxia-induced HIF1α stabilization, thereby enhancing tumoricidal activity of tumor infiltrating T cells." (PMID 26885366, 2016). "Whilst both cell lines in response to hypoxia showed nuclear localization of HIF-1α, we found also an intense cytoplasmic HIF-1α signal in DTC tumor cell line in normoxia." (PMID 27105499, 2016). "We show that the metabolic tumor marker TLG is significantly positively correlated to stromal HIF-1α protein expression." (PMID 27634881, 2016).
tumor (continued). "It thus seems conceivable that the hypoxic regions that develop in solid tumors contribute to hnRNP A18 up-regulation in the tumor and consequently up-regulation of its targeted transcripts such as HIF-1α." (PMID 26824423, 2016). "In line with our findings, in the MMTV-PyMT murine model, HIF-1α was shown to be necessary for acceleration of tumor onset and progression." (PMID 27105499, 2016). "When solid tumors encounter hypoxic conditions and HIF-1α is expressed, a number of processes occur to achieve tumor progression and an improved clinical stage." (PMID 27882053, 2016). "EAF2 also reportedly binds to and stabilizes von Hippel-Lindau protein (pVHL), a tumor suppressor involved in mediating HIF1α degradation and an inhibitor of the hypoxia pathway, which suggests it is a potential metabolic regulator." (PMID 27259264, 2016). "The results of our study suggest that hypoxia conditions can alleviate AgNPs-induced apoptosis in cancer cells via the HIF-1α-mediated autophagy pathway, which is an important regulatory event in tumor cells." (PMID 26867977, 2016). "To validate the in vivo function of HIF-1α methylation, we generate a methylation-deficient Hif1aKA/KA knock-in mouse and characterize the phenotypes of enhanced retinal angiogenesis and tumour growth and angiogenesis promotion via HIF-1α stabilization." (PMID 26757928, 2016). "Tumours expressed high levels of Vegfa and Hif1a indicating hypoxia, and developed a highly irregular vasculature." (PMID 27074663, 2016). "Previous studies have demonstrated that EAF2 binds to and stabilizes pVHL, a tumor inhibitor mediating HIF1α degradation." (PMID 27259264, 2016). "Nuclear immunoreactivity for HIF-1α was also detected in a significant number of tumor cells, and these cells were predominantly located adjacent to necrotic areas." (PMID 26799577, 2016). "More importantly, diacetoxyscirpenol retarded tumor growth in mice, and reduced HIF-1α expression and vascular formation in the tumors." (PMID 27613833, 2016). "The process of epithelial–mesenchymal transition (EMT), an important tumor progression program, can be activated by hypoxia, probably via a number of mechanisms such as HIF-1α signaling, in several human tumors and cell lines." (PMID 26760782, 2016). "CA IX is readily detected in PC tissues and correlates with the expression of HIF-1α, defining the protein a suitable marker of hypoxia in this tumor." (PMID 27225200, 2016). "High miR-210 was significantly associated with high HIF-1α protein (P=0.001), CA9 protein (P=0.0004), Glut-1 protein (P=0.001), 26-gene hypoxia score (P=0.007), tumour necrosis (P=0.02) and concurrent pTis (P=0.03)." (PMID 27441495, 2016). "The transcription factor HIF-1α, which targets 60 genes to enhance the tumour progression, angiogenesis, and metastasis, is regarded as the master regulator under the hypoxic environment." (PMID 27581969, 2016). "DEK promotes tumor angiogenesis and growth in nude mice in HIF-1α-dependent and -independent manners." (PMID 26988756, 2016). "Stabilisation of HIF1α under normoxia is mediated by miR-92-1 that targets the von Hippel–Lindau (VHL) tumour suppressor, an E3 ubiquitin ligase, which binds to HIF1α, thus inducing its degradation in the presence of oxygen." (PMID 27213336, 2016). "Prior treatment of tumor organ cultures with HIF-1α inhibitors decreased HIF-1α and FGF23 protein accumulation and inhibited HIF-1α-induced luciferase reporter activity in transfected cells." (PMID 27468359, 2016). "Lesions with high stromal HIF-1α expression exhibited increased tumor metabolism at FDG-PET/CT, and functional PET/CT and DCE-MRI parameters were correlated to previously published hypoxia gene signature scores." (PMID 27634881, 2016). "MCT4 is upregulated in hypoxia as a direct target of HIF-1α and functions to export lactate from hypoxic tumor cells." (PMID 27066484, 2016).
tumor (continued). "Because overexpression of HIF-1α in human tumors is associated with poor prognosis and treatment failure, the identification of the cofactors that trigger an epigenetic regulation of HIF-1α is mandatory to exploit tumor cell vulnerabilities." (PMID 26909598, 2016). "Our data supports this finding, demonstrating that hypotaurine acts to both potentiate HIF-1α stability and signaling as well as confer an invasive phenotype consistent with pseudohypoxia in tumor models." (PMID 26934654, 2016). "Several metabolic stressors including hypoxia, low pH, glucose level and molecules such as β2-Adrenogenic signaling and pyruvate kinase M2 (PKM2), induce HIF-1α expression results in tumor survival." (PMID 27367674, 2016). "On days 8, 16 and 24 after treatment, a higher expression of HIF-1α in the tumor microenvironment was found in the treatment group than in the control group." (PMID 27703219, 2016). "Our finding of high stromal HIF-1α expression in primary cancers and very low expression in premalignant lesions suggests that HIF-1α positive cells in the tumor stroma are important in early steps of endometrial carcinogenesis." (PMID 27634881, 2016). "Tumor stem cells’ self-renew is enhanced by hypoxia through HIF-1α, but their differentiation ability is reduced, thus leading to the accumulations of abundant tumor stem cells in MS hypoxic areas and ultimately promoting a more aggressive tumor phenotype." (PMID 26831659, 2016). "Because Salmonella can influence HIF-1α protein expression and thereby abrogate HIF-1α-mediated transcriptional activity in tumor cells, we wanted to identify the signaling pathway affected by Salmonella during tumor angiogenesis." (PMID 27175584, 2016). "Several small molecules were found to alleviate the hypoxic drug resistance and arrest the tumor xenograft growth through the inhibition of HIF-1α." (PMID 26771844, 2016). "By triple immunofluorescent staining in which NANOG was substituted for SOX2, a similar small subpopulation of tumor cells with a NANOG+ HIF-1α+ RNApII-S2P-/low phenotype was detected in the vicinity of necrotic areas." (PMID 26799577, 2016). "HIF-1α activation up regulates vascular epithelial growth factor (VEGF) expression, which manifests as the angiogenic hallmark in tumor biology." (PMID 26962408, 2016). "Tenascin-C expression in cancer cells was correlated with an increase in tumor-associated macrophage (TAM) population, cancer recurrence, and hypoxia inducible factor1α (HIF1α) expression." (PMID 26731558, 2016). "There is a positive feedback loop between hypoxia-inducible factor 1-alpha(HIF-1α) and lincRNA-p21 to promote tumor growth and the regulation of the Warburgeffect." (PMID 27508057, 2016). "PDGF also activates HIF1α, and c-Myc, increases glycolysis and suppresses the tumor suppressor Rb, resulting in modified tumor metabolism and increased proliferation." (PMID 27626684, 2016). "HIF-1α plays an important role in the process of angiogenesis while also supporting tumor cell survival and proliferation." (PMID 26918938, 2016). "In the previous studies, researchers found that the increased expression of HIF-1α contributed to the production of VEGF in tumor cells." (PMID 27413748, 2016). "The data also suggested a redistribution of subcellular localization for HURP and HIF-1α from the nucleus to the cytoplasmic compartment in relation to increasing tumor grade." (PMID 27379206, 2016). "The expression of HIF-1α in hypoxic conditions triggers genomic instability, angiogenesis, apoptosis, immune evasion, tumor invasion and metastasis, and the activation of glycolysis." (PMID 27882053, 2016). "In conclusion, giving the fact that Sirtuins regulate both HIF1α and NFκB and the central role that these two transcription factors have during tumor progression, the possibility to act on Sirtuins in order to control HIF1α and NFκB has drawn much attention." (PMID 26798421, 2016).
tumor (continued). "In contrast to this, the companion transcriptomic data indicated increasing HIF1A activation with ccRCC stage, though HIF1A mRNA levels were significantly decreased 1.25-fold in tumor tissue." (PMID 27128972, 2016). "A correlation between the oxygen-dependent subunit HIF-1α and tumor size as well as a poor prognosis of HCC has already been shown." (PMID 27027353, 2016). "Hypoxia plays a role in tumor growth and aggressiveness; adaptation to it is, at least to a large extent, mediated by hypoxia-inducible factor-1α (HIF-1α)." (PMID 27286880, 2016). "In the present study, we investigated the roles of CD133 in tumor migration via encouraging HIF-1α expression under hypoxia." (PMID 27367674, 2016). "In tumor cells, the hypoxia inducible factor-1α/pyruvate kinase M2 (HIF-1α/PKM2) axis plays an important role by supporting proliferation, angiogenesis and reprogramming of energy metabolism." (PMID 27602585, 2016). "mTOR is a downstream target of the PI3K–AKT signaling and has been demonstrated to enhance the expression of HIF1-α in immune cells recruited at the tumor lesion." (PMID 26870036, 2016). "For example, lncRNA-ENST00000480739 acts in cis to induce transcription of osteosarcoma amplified-9, which in turn acts in trans to suppress HIF-1α levels by increasing its degradation and thereby suppressing tumor cell invasion." (PMID 26590207, 2016). "Hif1α depletion results in rapid tumour growth with marked hypoxia-induced cell death, which potentially leads to a persistent tumour-sustaining inflammatory response." (PMID 27941931, 2016). "VEGFs can be produced by activated leukocytes and mesenchymal cells present in the tumor microenvironment or, more importantly, by tumor cells themselves under the influence of activated HIF1α and NFκB." (PMID 26798421, 2016). "An important driver for development of therapy resistance is the increase of tumor hypoxia during antiangiogenic treatment leading to the upregulation of the transcription factor hypoxia-inducible factor 1 alpha (HIF-1A)." (PMID 26956051, 2016). "Bioluminescence images from excised tumors after autopsy showed that luciferase signals in tumor tissues from PiB-treated mice were much lower, indicating reduced activation of HIF-1α." (PMID 26784107, 2016). "In RCC, galetin-1 can activate HIF-1α-mTOR signaling axis, enhance the migration ability of tumor cells, and promote tumor progression." (PMID 27259255, 2016). "This suggests that the niche harboring HIF-1α-regulated quiescent stem-like tumor cells is present near large ischemic necroses (“peri-necrotic niche”), potentially under the influence of oxygen diffusion from blood vessels." (PMID 26799577, 2016). "The fibroblasts expressing activated HIF1α also promoted xenograft tumour growth upon co-injection with breast cancer cells (MDA-MB-231) in nude mice." (PMID 27852311, 2016). "Previous evidence shows that HIF-1α is involved in breast tumorigenesis and modifies tumor growth rates and their metastatic potential." (PMID 26760782, 2016). "Hypoxia-inducible factor-1α (HIF-1α) is a critical mediator of the physiological response to hypoxia, and its dysregulation can promote tumor angiogenesis and metastasis." (PMID 26958938, 2016). "The fact that these five genes (MTHFD2, EIF4E, RMI1, CAV1 and HIF1A) are all very relevant in tumor biology further emphasizes a role of Wig-1 in the regulation of cell cycle and cell proliferation, as well as tumor onset, progression and metastasis." (PMID 26672765, 2016). "Tumour cells of the angiogenic phenotype displayed higher levels of hypoxic (HIF1α, HIF2α, MCT4) and angiogenic markers (VEGF, ANGPT2)." (PMID 27049916, 2016). "We put a special focus on the transcription factor HIF-1α, a master regulator of tumor angiogenesis." (PMID 27027353, 2016). "For EC, also when considering different cellular localization of HIF-1α (nuclear vs cytoplasm) in the tumor cells, results are conflicting." (PMID 27634881, 2016).